APBB1IP (amyloid beta precursor protein binding family B member 1 interacting protein)
Diseases named in the same sentence as APBB1IP in open-access papers:
APBB1IP is named in the same sentence as 31 diseases in open-access papers, as found by Europe PMC text mining. Sharing a sentence is not in itself a finding about the gene and the disease. The quoted sentences say what the papers report.
melanoma (6 papers, 2015 to 2024). A malignant, usually aggressive tumor composed of atypical, neoplastic melanocytes. "APBB1IP was reported to promote the migration and invasion of melanoma cells 7, and we speculated that APBB1IP might interact with VCL to achieve this function." (PMID 33391455, 2021). "However, APBB1IP also plays a central role in cancer cell migration and invasion, and APBB1IP-depleted melanoma cells displayed decreased persistent cell migration directionality, thereby reducing cancer invasion." (PMID 33391455, 2021). "APBB1IP is alternatively known as RIAM, silencing RIAM in melanoma cells leads to the inhibition of tumor growth and hinders metastasis in a mouse xenograft model combined with immunodeficiency." (PMID 33509178, 2021).
osteosarcoma (4 papers, 2021 to 2024). A usually aggressive malignant bone-forming mesenchymal neoplasm, predominantly affecting adolescents and young adults. "Bioinformatics analyses revealed that APBB1IP may be used as a potential biomarker for osteosarcoma metastasis and suggested its potential role in the evolutionary mechanisms of head and neck squamous cell carcinoma related to inflammation and TME." (PMID 37228491, 2023). "Immune-related APBB1IP was in relation to clinical outcomes of osteosarcoma patients." (PMID 34630511, 2021).
breast carcinoma (3 papers, 2020 to 2025). "Cathepsin E can mediate the effects of APBB1IP, NT5C3B, and ZNF66 on HER2-negative breast cancer, as well as the effects of DHRS9, CDK12, and CD247 on HER2-positive breast cancer." (PMID 39944834, 2025).
gastric cancer (3 papers, 2020 to 2022). A primary or metastatic malignant neoplasm involving the stomach. "Some studies have shown that APBB1IP is a new biological marker associated with gastric cancer and head and neck squamous cell carcinoma." (PMID 33425993, 2020). "In addition, APBB1IP is a signature gene that contributes to clinical gastric cancer (GC) diagnosis and early detection, and the PLD4 and PLD3 enzymes strongly affect inflammatory cytokine production via the degradation of nucleic acids, thus serving as important regulators of inflammatory disease." (PMID 34916564, 2021). "Furthermore, in a study on gastric cancer, 19 serum proteins, including APBB1IP, were used to distinguish patients with and without cancer." (PMID 39132059, 2022).
Clear Cell Renal Cell Carcinoma (2 papers, 2020 to 2022). "In a study on clear cell renal cell carcinoma, circular-APBB1IP was reported to be a prognostic biomarker promoting tumor growth and invasion through the activation of ERK1/2 signals." (PMID 39132059, 2022).
dementia (2 papers, 2020 to 2024). Loss of intellectual abilities interfering with an individual's social and occupational functions. "Furthermore, the hippocampal expression of Apbb1ip makes it a favorable candidate to discern the molecular pathophysiology of dementia in PD patients." (PMID 33101391, 2020).
Obesity (2 papers, 2016 to 2021). Accumulation of substantial excess body fat. "APBB1IP is commonly known as Rap1-GTPase, and plays a vital function in diet-induced obesity, insulin, and leptin resistance." (PMID 33669862, 2021). "APBB1IP, which encodes the Rap1-GTP-interacting adaptor, has been shown to be involved in regulating metabolism and protecting against obesity." (PMID 27467526, 2016).
sarcoma (2 papers, 2021). A usually aggressive malignant neoplasm of the soft tissue or bone. "The molecular characteristics of the four molecular subtypes were compared, and we determined three genes, namely, ENO1, ACVRL1 and APBB1IP, which were closely associated with the prognosis of sarcoma." (PMID 33509178, 2021). "RT-qPCR assay results indicated that ENO1 was upregulated, whereas ACVRL1 and APBB1IP were downregulated in Hs 729 sarcoma cells that in 10.014 pRSV-T cells." (PMID 33509178, 2021). "In our study, both high-expressed ENO1 and low-expressed APBB1IP were predictive of a poor sarcoma prognosis, suggesting that the three potential prognostic markers were closely associated with known genetic markers." (PMID 33509178, 2021). "Furthermore, the three potential prognostic markers (ENO1, ACVRL1 and APBB1IP) in predicting the sarcoma prognosis of different histological types were examined, due to the sample sizes of DT, MPNST, and SS, the prognostic role of the three genes were analyzed in DL, LMS, MFS and UPS." (PMID 33509178, 2021).
Stroke (2 papers, 2024). Sudden impairment of blood flow to a part of the brain due to occlusion or rupture of an artery to the brain. "APBB1IP (RIAM) is crucial for the proper activation and function of integrins in neutrophils, with its absence leading to impaired phagocytosis and its dysregulation potentially impacting stroke-induced neuronal injury and repair." (PMID 39595569, 2024).
atherosclerosis (1 paper, 2023). A disease characterized by the build-up of fatty material and calcium deposition in the arterial wall resulting in partial or complete occlusion of the arterial lumen. "Within the shared CAD/atherosclerosis liver network between species, APBB1IP, PTPRC, NCKAP1L and INPP5D were captured as potential novel KDs which again have not been strongly investigated, validated or implicated in CAD previously." (PMID 38060277, 2023).
cholesteatoma (1 paper, 2022). A pathologic process characterized by the proliferation of keratinizing squamous epithelium resulting in the accumulation of keratin and cells in the middle ear and/or mastoid. "However, in our own middle ear expression dataset from the same patients, all 12 genes were DEGs for cholesteatoma: RTN4, RAB5A, CRYBG1, RGS22, HEPHL1, and SPTLC3 were upregulated, while APBB1IP, BHLHE41, ARID3A, C5AR1, CPT1B, and FAM227A were downregulated." (PMID 36699445, 2022).
colon cancer (1 paper, 2017). "This is the first evidence supporting a role for PTPRC, APBB1IP, LCP2, miR-30a-3p, and miR-30e-3p in colon cancer metastasis." (PMID 28629469, 2017). "Therefore, APBB1IP, LCP2, and PTPRC might also play a role in colon cancer metastasis." (PMID 28629469, 2017).
colorectal cancer (1 paper, 2022). A primary or metastatic malignant neoplasm that affects the colon or rectum. "In another study on colorectal cancer using cell-free DNA, hypermethylation of APBB1IP was identified as a novel candidate for cancer detection." (PMID 39132059, 2022).
lung carcinoma (1 paper, 2021). "Multivariate Cox regression analyses were applied to construct a prognostic model, which consisted of APBB1IP and its interacting proteins, based on the lung cancer cohorts from the Gene Expression Omnibus (GEO) database." (PMID 33391455, 2021).
schizophrenia (1 paper, 2019). A major psychotic disorder characterized by abnormalities in the perception or expression of reality. "Our results suggest that APBB1IP is involved in cell motility, the immune response and neuronal development, all of which have been linked to schizophrenia." (PMID 31920576, 2019). "This shows that two variants in APBB1IP are significantly associated with self-reported schizophrenia (UKBB ID 20002_1289)." (PMID 31920576, 2019). "For each tissue, we recorded the overlap in genes coexpressed with Apbb1ip and with genes associated with schizophrenia." (PMID 31920576, 2019). "We can next take advantage of massive gene expression datasets to identify plausible mechanisms by which APBB1IP may be linked to schizophrenia." (PMID 31920576, 2019). "This further supports APBB1IP as a schizophrenia associated gene." (PMID 31920576, 2019). "Our systems genetics approach demonstrates that APBB1IP coexpresses with several other genes related to schizophrenia in several brain regions, providing a potential mechanism of action." (PMID 31920576, 2019). "We identified one gene (amyloid-β precursor protein-binding family B member 1 interacting protein; APBB1IP) that was significantly associated with PPI in mice and the risk of schizophrenia in humans at the genome-wide level." (PMID 31920576, 2019). "A systems genetics approach demonstrates that APBB1IP coexpresses with several other genes related to schizophrenia in several brain regions." (PMID 31920576, 2019). "Apbb1ip is found to be expressed in homologous tissues to ABPP1IP, particularly the dentate gyrus, previously linked to schizophrenia." (PMID 31920576, 2019). "In summary, the combination of human GWAS and mouse QTL from some of the largest study systems available has enabled us to identify a novel gene, APBB1IP, which influences schizophrenia in humans and PPI in mice." (PMID 31920576, 2019). "Although we have identified genes that are coexpressed with Apbb1ip and are enriched for annotations linked to schizophrenia, this does not directly link them with schizophrenia." (PMID 31920576, 2019). "We have identified APBB1IP, on chromosome 10 in humans and chromosome 2 in mice, as a novel gene that influences schizophrenia in humans and PPI in mice, and identified a number of genes which may be involved in this association." (PMID 31920576, 2019). "Next, we investigated the homologous genomic regions in human schizophrenia GWAS data and were able to identify one novel candidate gene, APBB1IP (also referred to as PREL1, RARP1, and RIAM; Entrez 54518)." (PMID 31920576, 2019).
tumor (11 papers, 2012 to 2025). "Here, we conducted a pan-cancer analysis of the expression profile and prognostic significance of APBB1IP and revealed its potential role in tumor immunology via bioinformatics analysis." (PMID 33391455, 2021). "After adjustments for tumor purity, APBB1IP expression was significantly correlated with most immune cell markers in SKCM, in addition to several markers of M1 macrophages and neutrophils." (PMID 33391455, 2021). "They finally determined that five out of the seven mRNA, i.e. Apbb1ip, Aspn, Incenp, Daf2, and Foxp1, were significantly upregulated (p < 0.05) in saliva-derived exosomes of tumor-bearing mice." (PMID 33297544, 2020). "Our results suggested that circ-APBB1IP was overexpressed in ccRCC tumor tissues and ccRCC cell lines, and circ-APBB1IP promoted ccRCC cells growth, migration, and invasion and suppressed apoptosis via ERK1/2 signaling pathway." (PMID 32547313, 2020). "Moreover, the correlation between APBB1IP and the expression of immune regulators indicate a role of APBB1IP in regulating tumor immunology in different cancers." (PMID 33391455, 2021). "APBB1IP upregulation was correlated with increased immune-cell infiltration, and the expression APBB1IP in different tumors might be related to the tumor immune microenvironment." (PMID 33391455, 2021). "The expression of circ-APBB1IP in ccRCC cell lines 786-O and Caki-1 was significantly higher than that in normal renal cell line HK-2, and a similar pattern was seen in 11 pairs ccRCC tumor tissues and tumor-distant tissues." (PMID 32547313, 2020). "However, the role of APBB1IP in tumor immunity remains unclear." (PMID 33391455, 2021).
cancer (9 papers, 2015 to 2025). A tumor composed of atypical neoplastic, often pleomorphic cells that invade other tissues. "First of all, we used univariate Cox proportional hazard regression models to analyze the association between APBB1IP expression with the overall survival and progression-free survival in various cancers in the TCGA." (PMID 33391455, 2021). "The expression of TLN1 and TLN2 was positively associated with CNV in most cancers, except for APBB1IP, RAP1B, and RAP1A." (PMID 33391455, 2021). "Moreover, we report, for the first time, the association of IL12RB1, CA11, CD276, and APBB1IP with cancer-associated inflammation." (PMID 37228491, 2023). "In addition, miR-200b-5p was identified as possibly targeting APBB1IP and it was negatively associated with the expression of APBB1IP in most cancers." (PMID 33391455, 2021). "Moreover, cancer-related inflammation may cause the downregulation of APBB1IP decreasing the recruitment of leukocytes to the TME." (PMID 37228491, 2023). "Using STARBASE v3.0 with p < 0.05 as screening criteria, we investigated the Spearman correlation between miRNAs and the expression of APBB1IP in 32 kinds of cancers from TCGA." (PMID 33391455, 2021). "Other interactors include Rap1-interacting adapter molecule (RIAM; also known as APBB1IP), deleted in liver cancer 1 (DLC1), and cyclin dependent kinase 1 (CDK1) (see poster and Box 1 for more details)." (PMID 34708856, 2021). "The results revealed that the expression of APBB1IP was inconsistently up- or down-regulation in different cancer types." (PMID 33391455, 2021). "Multiple correlation-based studies have implicated APBB1IP in signaling events critical for integrin-mediated control of immune function 4, 6, and these findings support a prognostic role of APBB1IP in cancer." (PMID 33391455, 2021). "Another important finding of this study is that APBB1IP expression is correlated with diverse immune-cell infiltration levels in most cancer types." (PMID 33391455, 2021). "We next investigated the prognostic value of APBB1IP via pan-cancer analysis in different databases." (PMID 33391455, 2021). "In this study, we evaluated the expression signature and prognostic value of the APBB1IP gene in pan-cancer analysis using the TCGA pan-cancer database and Kaplan-Meier Plotter." (PMID 33391455, 2021). "Higher APBB1IP expression in most cancers markedly increased the infiltration of immune cells, especially in BRCA, CESC, HNSC, PRAD, SKCM, TGCT and UCEC." (PMID 33391455, 2021). "The results indicated that APBB1IP expression is positively correlated with both immunoinhibitory and immunostimulatory factors in the majority of cancers." (PMID 33391455, 2021). "This study was carried out to evaluate the prognostic landscape of APBB1IP in pan-cancer analysis and investigate the relationship between APBB1IP expression and immune infiltration." (PMID 33391455, 2021). "APBB1IP integrates signaling events that are critical for integrin-mediated immune function control and cancer progression." (PMID 33425993, 2020). "It was shown that expression of APBB1IP was correlated with the prognosis of various cancer types and its upregulation has been demonstrated as associated with increased immune cell infiltration, especially CD8+ T cells, natural killer (NK) cells, and immune regulators." (PMID 37228491, 2023). "It is worth noting that IL12RB1, CD276, and APBB1IP are involved in cancer surveillance, inhibition of T-cell mediated responses, and T-cell recruitment, respectively, whereas CA11 may induce proliferation and invasion of gastrointestinal tumors." (PMID 37228491, 2023). "The discrepancies in APBB1IP levels and prognosis in different cancer types in different databases might be a reflection of different data collection approaches and underlying mechanisms pertinent to different biological properties." (PMID 33391455, 2021).
cancer (continued). "In this study, the expression levels of APBB1IP were examined and the prognostic landscape in pan-cancer analysis were visualized using independent datasets in Oncomine and Kaplan-Meier plotter, as well as TCGA data for 33 types of cancer." (PMID 33391455, 2021). "It is likely that APBB1IP might influence the progression of cancer by influencing the regulation of immune infiltration." (PMID 33391455, 2021). "Notably, APBB1IP was up‐regulated in KIRP, but high APBB1IP expression indicated a better prognosis in this cancer." (PMID 33391455, 2021). "Hence, future prospective studies are needed to explore the relationship between APBB1IP expression and immune infiltration in a cancer patient population." (PMID 33391455, 2021). "Next, we could not prove that APBB1IP affected patient survival through immune infiltration even though we found that APBB1IP expression was correlated with both immune cell infiltration and patient survival in cancers." (PMID 33391455, 2021). "However, there are no systemic studies on the role of APBB1IP in different human cancers, and it remains unclear whether the effects of APBB1IP might be context-dependent, varying in different cancers." (PMID 33391455, 2021). "In accordance with our recent study, DIO1 expression resulted also in suppression of TGFBI, and several other proteins (e.g. PODXL, CD74) that promote RCC progression or act as oncogenic proteins in other cancers (e.g. FMNL2, APBB1IP, ASAP1, and LRRFIP1)." (PMID 29272308, 2017). "Finally, we only conducted a bioinformatic analysis of APBB1IP expression and patient survival across different databases, and further mechanistic studies on APBB1IP at the cellular and molecular levels could help clarify its functions in cancer initiation and progression." (PMID 33391455, 2021). "For APBB1IP, the SNV frequency was 20%, at the cancer level." (PMID 33391455, 2021). "Interestingly, although the prognostic implications of APBB1IP were not the same in different cancer types, APBB1IP expression was consistently positively correlated with the immune-cell infiltration levels in these cancers." (PMID 33391455, 2021).
APBB1IP also shares sentences with these, for which no sentence is quoted: head and neck squamous cell carcinoma (2 papers); infection (2); leukocytosis (2); cerebral cavernous malformation (1); CNS cancers (1); coronary heart disease (1); gastrointestinal tumors (1); heart disease (1); Immunodeficiency (1); leukemia (1); leukocyte adhesion deficiency (1); liver cancer (1); otitis media (1); thymoma (1).